GADD45B (growth arrest and DNA damage inducible beta)
Diseases named in the same sentence as GADD45B in open-access papers (continued):
Sharing a sentence is not in itself a finding about the gene and the disease.
cancer (continued). "However, the increased expression of GADD45B, ITGB5, MMP1, and BNDF was correlated with a decreased chemotherapy resistance of cancer cells to mithramycin, tramrtinib, ARRY-162, dabrafenib, selumetinib, vemurafenib, nilotinib, coimetinib, cyclophosphamide, oxaliplatin, and tamoxifen." (PMID 35699863, 2022). "The fact that GADD45B and GADD45A were significantly overexpressed in both cell lines after fisetin treatment could explain that induction of cell cycle arrest was among mechanisms modulating the anti-tumor activity of fisetin on cancer cell lines." (PMID 28052097, 2017). "In addition, the effects of GADD45β gene activation in cell cycle arrest increase proportionally with the dose of SFN; however, mitotic delay and the inhibition of proliferation both depend on the dosage of SFN used to treat cancer cells." (PMID 27626412, 2016). "Taken together, our results suggest that the inhibition of both ABCG2 and GADD45β might be used as a new target for curative therapy without recurrence or metastasis through the targeting of cancer stem-like cells, such as SP cells." (PMID 21048853, 2010). "Indeed, Gadd45b−/− HCC tumors, but not Gadd45b+/+ tumors, showed an enhanced F4/80+ and IBA1+ TAMs and T-cells infiltration as well as a higher number of tertiary lymphoid structures (TLSs), which are correlated to a favorable clinical outcome in most human cancers." (PMID 38397187, 2024).
tumor (72 papers, 2005 to 2026). "Since this work relies on publicly available data, although this study’s findings confirmed GADD45B’s role in tumor immune modulation and immunotherapy, more research is necessary to understand the underlying molecular process of GADD45B in SKCM." (PMID 40350499, 2025). "On the other hand, ATF3, BHLHE40, ZNF263, and FOXP2 transcription factors were strongly associated with GADD45B-low tumor cells." (PMID 37608794, 2023). "GADD45B-high tumor cells showed strong associations with transcription factors such as ELK1, PAX5, SMAD3, BACH1, and NR1H2." (PMID 37608794, 2023). "A plethora of NMD targets have been identified, with several being linked to apoptotic and cell cycle arrest effects, such as GADD45b and the tumor suppressor lncRNA GAS521–23." (PMID 37349371, 2023). "Tsc22d1 encodes a leucine zipper transcription factor that plays a role in tumor suppression and Gadd45b encodes a protein involved in the regulation of growth and apoptosis." (PMID 29706024, 2018). "Another potential novel target gene, GADD45B, highly induced and coexpressed with the fibrosis related genes in this study, is a pro-survival factor associated with stress-resistant tumours, and has been found to be upregulated in SSc skin biopsies." (PMID 23915349, 2013). "Furthermore, we identified the most significant transcription factors associated with GADD45B-high tumor cells and GADD45B-low tumor cells." (PMID 37608794, 2023). "Therefore, we analyzed PB-induced transcriptome responses of wild type and Gadd45β null mutant mice livers expecting to find the key gene expression changes derived from the null mutation resulted in altered tumor development." (PMID 37746289, 2023). "We found that GADD45B-high GC cells had closer communication with other cells in the tumor microenvironment than GADD45B-low GC cells, with vascular endothelial cells, tumor-associated fibroblasts, and tumor-associated macrophages serving as the primary signal-transmitting cells." (PMID 37608794, 2023). "As a stress-response gene, GADD45B might be continuously activated with the accumulation of DNA damage and loss its normal function in the tumor progression." (PMID 33330109, 2020). "For example, GADD45B was positively involved in G2/M-phase arrest and apoptosis through induction of cyclin-dependent kinase inhibitor 1 A expression; and it has been reported to be a promising tumor suppressor in NSCLC and has close association with NSCLC development." (PMID 38167059, 2024). "Growth Arrest and DNA Damage-inducible beta (GADD45β) is a stress-responsive, NF-κB-inducible gene known to modulate inflammation and tumor progression by inhibiting MKK7 to block JNK signaling and influence macrophage polarization and T-cell recruitment." (PMID 41354733, 2025). "Mice injected with GADD45B-overexpressing tumor cells exhibited smaller tumor volumes from day 15 onwards compared to controls, with markedly reduced tumor volume and weight at the endpoint." (PMID 40350499, 2025). "Emerging evidence suggests that GADD45B plays a significant role in modulating immune responses within the tumor microenvironment." (PMID 40350499, 2025). "To confirm that EBV-miR-BART19-3p plays a tumor growth role by inhibiting GADD45B, we transfected the GADD45B expression vector into AGS and GES cells." (PMID 40855561, 2025). "Its anti‐tumour effects primarily work through the modulation of various signalling pathways and activation of Gadd45β." (PMID 39653679, 2024). "Compared with wild‐type mice, Gadd45β−/− mice exhibited less liver proliferation and tumour development and significantly reduced hepatocyte proliferation induced by PB." (PMID 39653679, 2024). "Early drug damage led to increased Gadd45β expression, whereas a decrease in Gadd45β was witnessed in subsequent tumour development." (PMID 39653679, 2024). "This reflects the general preference for Gadd45β, which is widely recognised for promoting tumour apoptosis and regulating cell cycle." (PMID 39653679, 2024).
tumor (continued). "This evidence suggests targeting Gadd45β as a potential strategy for treating HCC, by enhancing tumour apoptosis through Gadd45β upregulation." (PMID 39653679, 2024). "Despite exhibiting contradictory results in tumour cells and immune cells, the impact of Gadd45β on tumour cells comes not only from the tumour cells themselves, but also through the assistance of other immune cells." (PMID 39653679, 2024). "To investigate the impact of GADD45B on the differentiation trajectory of tumor cells, we performed pseudo-time series analysis on these three cell types." (PMID 37608794, 2023). "We have observed that SMG7 is required for targeting GADD45b and the tumor suppressor lncRNA GAS5 for degradation in our cells." (PMID 37349371, 2023). "HCC was observed in only WT mice; thus, these results suggest that Gadd45β plays critical roles in PB-induced tumor promotion." (PMID 37746289, 2023). "Studies have demonstrated that low expression of GADD45B in normal tissues promotes carcinogenesis, whereas high expression in malignant tissues contributes to tumor development." (PMID 37608794, 2023). "The upregulation of several known immune checkpoints was observed in the high-expression group of GADD45B, suggesting more severe immunosuppression in the tumor microenvironment of patients with high GADD45B expression." (PMID 37608794, 2023). "Gourabine E retards mitosis in human glioblastoma cell tumor cells by upregulating the expression of Gadd45b, thereby inhibiting tumor growth." (PMID 36311022, 2022). "GADD45B is an oncogene in ovarian cancer, but it is a tumor suppressor gene in liver cancer, non-small cell lung cancer, and PCa." (PMID 34490266, 2021). "Inhibits Treg-mediated immune escape of tumor cells through upregulating GADD45B by sponging miR-423-5p." (PMID 34295338, 2021). "GADD45B, a stress response gene and a tumor suppressor was significantly downregulated in SF1 tumors." (PMID 34758873, 2021). "On the other hand, increased GADD45B expression has been related to chemotherapy resistance and survival of tumor cells resistant to ultraviolet light and gamma radiation in medium with low nutrient availability." (PMID 32425887, 2020). "The mechanism of CuE involvement in the inhibition of tumour growth was highlighted by the delay of mitosis via the up‐regulation of GADD45β expression." (PMID 30912292, 2019). "GADD45B shares the common functions of the GADD45 family, which is associated with DNA damage repair, cell growth, apoptosis, and anti-tumor immune responses." (PMID 30029519, 2018). "Knockdown of GADD45B/G largely abolished synergistic anti-tumor effect of JQ1 and Bortezomib co-treatment in vivo." (PMID 29472532, 2018). "At the same time, with the accumulation of DNA damage in tumor progression, the GADD45B expression level will improve feedback." (PMID 30029519, 2018). "We showed that macrophage-associated GADD45β expression governs an innate-immunity checkpoint restricting TME-based inflammation and T-lymphocyte trafficking into tumours, the major barrier to effective immunotherapy." (PMID 29511335, 2018). "We identified a dedicated axis of the NF-κB pathway, mediated by GADD45β, which integrates the NF-κB-dependent mechanism suppressing tumour-cell apoptosis with that governing tumour-based inflammation." (PMID 29511335, 2018). "From these results, we confirmed that expression of Gadd45β was significantly decreased in human liver tumor cells and tissues, when compared to normal liver cells and peri-tumor tissues." (PMID 29225771, 2017). "We have demonstrated earlier that the combinatorial therapy with aspirin and sorafenib decreased the expression of ACSL4 and increased the expression of GADD45B to result in the inhibition of tumor growth." (PMID 28900541, 2017).
tumor (continued). "Furtherly, western blot results also showed the down-regulation of Gadd45β expression in tumor tissues, when compared to the peri-tumor tissues." (PMID 29225771, 2017). "Defects of the growth arrest DNA damage-inducible gene 45β (Gadd45β) play an important role in the progression of tumor and confer resistance to chemotherapy." (PMID 29225771, 2017). "Gadd45 proteins were originally reported as a pro-apoptotic protein; but recent studies showed that Gadd45α and Gadd45β increased tumor cell survival under treatment with chemotherapeutic drugs." (PMID 29225771, 2017). "The MSP primers were designed according to previous report; the methylation-specific PCR (MSP) assay was performed in the selected clinical tumor specimens and surrounding peri-tumor tissues to qualitatively observe the methylated status of Gadd45β promotor." (PMID 29225771, 2017). "It was found that Gadd45α and Gadd45β proteins play a dual role in the apoptosis of tumor cells induced by genotoxic stress, showing both apoptotic and antiapoptotic function." (PMID 29225771, 2017). "Various human tumor studies have shown that GADD45β was aberrant and while GADD45β has clear features of tumor suppression." (PMID 27655697, 2016). "The level of downregulation of growth arrest DNA damage-inducible gene 45β (GADD45b) in HCC is strongly correlated with increased tumor malignancy." (PMID 27177086, 2016). "GADD45β is necessary for full expression of the Th1 lineage-inducing proteins which include T-bet, and Eomes, and is important for anti-tumor immune responses." (PMID 27655697, 2016). "The mRNA expression levels of GADD45α, GADD45β, GADD45γ in tumor tissue and adjacent normal tissue from ESCC were detected." (PMID 22313682, 2012). "Given its role in macrophage polarization towards the M1 phenotype, GADD45B could potentially modulate the tumor immune microenvironment and enhance anti-tumor immunity." (PMID 40350499, 2025). "Mechanistically, GADD45B may exert anticancer effects by regulating macrophage viability and participating in tumor immunotherapy." (PMID 40350499, 2025). "TCGA was used to analyze GADD45B expression in normal and tumor tissues." (PMID 40350499, 2025). "In addition, correlation analysis showed that GADD45B was positively correlated with inflammation and apoptosis but negatively correlated with tumor proliferation." (PMID 40350499, 2025). "Furthermore, in vivo experiments using a xenograft mouse model demonstrated that GADD45B overexpression significantly suppressed tumor growth." (PMID 40350499, 2025). "Tsc‐22 is a tumour suppressor gene that represents a novel kind of transcription factor that has transcriptional repressor activity and may suppress Gadd45β which may contribute to an early antiapoptotic response." (PMID 39653679, 2024). "Analysis showed that the differentiation trajectories of GADD45B-high tumor cells and GADD45B-low tumor cells were essentially the same, but further Beam tests indicated that GADD45B played an important role in the differentiation and development process of GC cells (P<0.05)." (PMID 37608794, 2023). "Targeting GADD45B in treatment strategies might prove effective in restoring abnormal metabolic capacities within tumor tissues." (PMID 37608794, 2023). "Moreover, GADD45B expression levels were closely tied to poor prognosis in GC patients, influencing the infiltration patterns of various cells within the tumor microenvironment, as well as impacting the metabolic pathways involved in GC progression." (PMID 37608794, 2023). "Tumor cells with expression values above the median were categorized as GADD45B-high, while those with expression values below the median were classified as GADD45B-low." (PMID 37608794, 2023). "Furthermore, GC tissues with high expression of GADD45B frequently exhibited immune checkpoint upregulation and significant suppression of anti-tumor immunity, as evidenced by statistically significant differences." (PMID 37608794, 2023).
tumor (continued). "Next, we stratified the tumor cells based on the expression level of GADD45B." (PMID 37608794, 2023). "We hypothesized that GADD45B might play a significant role in regulating the tumor microenvironment in GC." (PMID 37608794, 2023). "Considering this immunological dysfunction and substantial suppression of anti-tumor immunity, immunotherapy might hold promise as a significant treatment for patients with GC displaying high expression of GADD45B." (PMID 37608794, 2023). "Gadd45b promotes gonadotrophic tumor apoptosis, primarily by arresting cells in G1/S and G2/M phases, but its upstream regulatory pathways are unknown." (PMID 36311022, 2022). "Based on these observations, we hypothesize that the toxic species formed by GADD45β at physiological temperatures might represent a protection mechanism toward the pro-survival role played by this protein in several tumor tissues." (PMID 34639041, 2021). "The downregulation of the N-Myc, Egr1, Sox9 mRNAs and the upregulation of Gadd45b mRNA in tumor-bearing mouse heart could conceivably be important in reducing cardiac growth and differentiation." (PMID 31851697, 2019). "We also analyzed tumor immunophenotype of patients with gene alteration like GADD45B." (PMID 31681565, 2019). "Notably, our finding that GADD45β also mediates a TME-based innate-immunity checkpoint provides an attractive therapeutic route downstream of NF-κB to reactivate anti-tumour immune responses." (PMID 29511335, 2018). "Moreover, as mentioned in the discussion above, inhibition of the GADD45B expression leads to suppression of proliferation and further prohibits tumor progression." (PMID 30029519, 2018). "Furthermore, according to the staining pattern of Gadd45β d, we found that the peri-tumor tissue showed 80% (80 of 100) positive staining, while tumor tissue showed only 20% (20 of 100) positive staining." (PMID 29225771, 2017). "Furthermore, the results showed that HCC tissues and cell lines showed a higher methylation status in Gadd45β promoter than that in peri-tumor tissues and normal liver cells." (PMID 29225771, 2017). "By contrast, although NF-κB-dependent control of JNK activity in the liver has been linked to regulation of its target gene Gadd45β,17 we did not observe any changes in its expression in RelA T505A tumours." (PMID 26853469, 2016). "Down-regulation of GADD45B has been associated with neoplasia; however levels of GADD45B were not significantly dysregulated in the BRK cell line stably transformed by oncogenic Ad12 E1 in comparison to untransformed BRK." (PMID 19200380, 2009). "As down-regulation of GADD45B is associated with neoplasia, it is perhaps not surprising that GADD45B was found to be significantly up-regulated in BRK cells stably transformed with the non-oncogenic Ad5 E1 region." (PMID 19200380, 2009). "The list of genes with reduced expression in DA, as compared with increased expression in DA.F344(Cia5d) congenics, included seven genes that are involved in tumor suppression-like activity and cell cycle check-points, such as Aph1a, Brwd3, Gadd45b, Gmfg, Lox, and Plekhg2." (PMID 18706093, 2008). "Thus, DUSP4 is a context-specific tumor suppressor that is dependent on the activity of GADD45B." (PMID 41523653, 2026). "Nevertheless, the exact influence of Gadd45β on tumour initiation remains unclear." (PMID 39653679, 2024). "Whether the hsa-miR-300—GADD45B still regulates tumor development by cell cycle pathway is unclear." (PMID 38070141, 2023).